ASB10 (ankyrin repeat and SOCS box containing 10)
Description:
May be a substrate-recognition component of a SCF-like ECS (Elongin-Cullin-SOCS-box protein) E3 ubiquitin-protein ligase complex which mediates the ubiquitination and subsequent proteasomal degradation of target proteins.
Synonyms: GLC1F
Tractability: No criterion of Open Targets' tractability assessment is met for any kind of drug.
Gene: Protein-coding gene on chromosome 7 (151,175,695 to 151,187,832, reverse strand). Ensembl gene ENSG00000146926.
Subcellular location: Cytoplasm; Nucleus
Pathways (Reactome):
Immune System: Antigen processing: Ubiquitination & Proteasome degradation
Metabolism of proteins: Neddylation
Gene Ontology:
Molecular function: protein binding
Biological process: intracellular signal transduction; protein ubiquitination
Cellular component: cytoplasm; nucleus; cytosol
Genetic constraint (gnomAD): Loss-of-function variants: 44 observed, 34.6 expected, observed/expected ratio (o/e) 1.27, 90% interval 1 to 1.63. The upper end of that interval is the gene's LOEUF score, 1.63, which puts it in group 6 of 6, group 1 being the genes least tolerant of losing a copy. Missense variants: 647 observed, 630.95 expected, observed/expected ratio (o/e) 1.03, 90% interval 0.96 to 1.09. Synonymous variants: 294 observed, 275.7 expected, observed/expected ratio (o/e) 1.07, 90% interval 0.97 to 1.17.
Homologues: Orthologues: chimpanzee ASB10 (99% identical), macaque ASB10 (97% identical), dog ASB10 (90% identical), rabbit ASB10 (88% identical), pig ASB10 (88% identical), guinea pig ASB10 (87% identical), mouse Asb10 (84% identical), rat Asb10 (83% identical), chimpanzee ASB10 (79% identical), tropical clawed frog asb10 (45% identical), zebrafish asb10 (41% identical). Paralogues in human: ASB18 (41% identical), ASB16 (35% identical), ASB4 (29% identical), ASB14 (24% identical), ASB15 (22% identical), ASB3 (21% identical), MPHOSPH8 (19% identical).
Diseases named in the same sentence as ASB10 in open-access papers:
ASB10 is named in the same sentence as 30 diseases in open-access papers, as found by Europe PMC text mining. Sharing a sentence is not in itself a finding about the gene and the disease. The quoted sentences say what the papers report.
glaucoma (11 papers, 2011 to 2025). Increased pressure in the eyeball due to obstruction of the outflow of aqueous humor. "There are no studies implicating this gene with stroke risk, however, a synonymous variant in ASB10 has been associated with primary open angle glaucoma." (PMID 30237808, 2018). "Further studies in other populations are required to better understand the role of ASB10 gene variants in glaucoma." (PMID 26713451, 2015). "The aim of the current study was to assess the role of ASB10 gene variants in Pakistani glaucoma patients." (PMID 26713451, 2015). "Ankyrin repeat and suppressor of cytokine signaling (SOCS) box containing protein-10 (ASB10) was recently identified as a gene that causes primary open-angle glaucoma." (PMID 23901248, 2013). "For example, sequence variations in the ankyrin repeat region and the SOCS box of ASB10, among others, alter protein stability and cellular localization and could be associated with glaucoma development." (PMID 35832195, 2022). "Non-synonymous variants identified in the ASB10 gene in glaucoma patients." (PMID 26713451, 2015). "This supports previous findings that sequence variants in the ASB10 gene may act as a risk factor for glaucoma." (PMID 26713451, 2015). "This study replicates the previous findings that sequence variants in the ASB10 gene may act as a risk factor for glaucoma." (PMID 26713451, 2015). "This outflow rate reduction when using lentivirus to silence full-length transcripts is consistent with our hypothesis that loss of full-length ASB10 may contribute to IOP increases in patients with glaucoma." (PMID 23901248, 2013). "A recent paper questioned whether ASB10 is a glaucoma susceptibility gene." (PMID 23901248, 2013). "To date, more than 15 loci have been identified for glaucoma, and the causative gene has been identified for 5 of these loci: GLC1A (MYOC/TIGR), GLC1E (OPTN), GLC1F (ASB10), GLC1G (WDR36), and GLC1H (EFEMP1)." (PMID 28150229, 2018). "Analysis of the ASB10 gene in 30 probands (one per family) of Pakistani glaucoma families revealed six nonsynonymous, two synonymous, and two intronic variants." (PMID 26713451, 2015). "In the current study we further investigated the role of the ASB10 gene in glaucoma families and sporadic POAG patients from Pakistan." (PMID 26713451, 2015). "In a recent study, ASB10 was identified as a novel gene for glaucoma at the GLC1F locus." (PMID 26713451, 2015). "This may indicate that the interaction of ASB10 with its substrates and recruitment of the ubiquitin ligase complex may be compromised in some patients with glaucoma." (PMID 23901248, 2013). "Yet, because the frequency of variants identified in the NHLBI ESP is similar to that found in the Iowa glaucoma population (2.53% compared to 2.34%), the authors ruled out ASB10 as a glaucoma susceptibility gene." (PMID 23901248, 2013). "No discernible differences in the colocalization of large ASB10-stained structures with ubiquitin or HDAC6 were observed between dermal fibroblasts derived from a normal individual and a patient with primary open-angle glaucoma carrying a synonymous ASB10 mutation." (PMID 23901248, 2013). "WD repeat domain 36 (WDR36), neurotrophin 4 (NTF4), ankyrin repeat and SOCS box-containing 10 (ASB10), and TANK-binding kinase 1 (TBK1) are other genes that have also been reported to be glaucoma-causing genes, but are controversial or have not yet been widely replicated." (PMID 22509100, 2012).
breast tumor (1 paper, 2021). "Assessment of ASB10 expression in BC patient tissues showed that ASB10 expression was highest in luminal breast tumor tissues, and lowest or absent in HER2+ or TNBC breast tumor tissues." (PMID 34285210, 2021).
cardiac hypertrophy (1 paper, 2025). "We next aimed to elucidate the molecular mechanism underlying the phenotype that Asb10 exacerbates cardiac hypertrophy." (PMID 40399264, 2025). "In this study, we aimed to elucidate the role of Asb10 in pathological cardiac hypertrophy and heart failure by using gain- and loss-of-function approaches and further explore the underlying molecular mechanisms through high-throughput protein interaction analyses." (PMID 40399264, 2025). "As a cardiac tissue-enriched E3 ligase, whether Asb10 is associated with pathological cardiac hypertrophy and heart failure remains unknown." (PMID 40399264, 2025). "Our study extends the understanding of the mechanisms underlying cardiac hypertrophy and provides a potential strategy of targeting the Asb10/HSP70 axis for the treatment of cardiac hypertrophy and heart failure." (PMID 40399264, 2025). "Taken together, these findings suggest that cardiac overexpression of Asb10 aggravates cardiac hypertrophy in response to hemodynamic stress." (PMID 40399264, 2025). "In this study, we reported that Asb10 plays a critical role in the pathogenesis of cardiac hypertrophy and heart failure." (PMID 40399264, 2025). "Taken together, all these RNA-sequence data revealed that Asb10 is significantly downregulated in pathological cardiac hypertrophy." (PMID 40399264, 2025). "In another cardiac hypertrophy model induced by ET-1 stimulation, the expression of Asb10 was also substantially downregulated." (PMID 40399264, 2025). "Through integrated bioinformatic screening of GEO datasets and experimental verifications, we identified Asb10 as the downregulated gene in cardiac hypertrophy." (PMID 40399264, 2025). "Our data further revealed that Asb10 is downregulated in cardiac hypertrophy and heart failure, whereas its overexpression results in more severe pathological cardiac remodeling following pressure overload, indicating its protective role in these processes." (PMID 40399264, 2025). "Consistent with the previous in vitro results, the expression of Asb10 showed a progressive decrease over the course of cardiac hypertrophy development." (PMID 40399264, 2025). "Overexpression of Asb10 aggravates pressure overload-induced pathological cardiac hypertrophy by directly interacting with HSP70 and competitively inhibiting STUB1-mediated ubiquitin-dependent degradation of HSP70." (PMID 40399264, 2025). "Future studies are warranted to fully address the role of HSP70 in Asb10 overexpression-mediated cardiac hypertrophy by utilizing cardiac-specific HSP70 KO mice." (PMID 40399264, 2025). "Collectively, these findings suggest that Asb10 is downregulated in pathological cardiac hypertrophy and heart failure." (PMID 40399264, 2025). "Here, we aimed to dissect the role of Asb10 in the pathogenesis of cardiac hypertrophy and heart failure." (PMID 40399264, 2025). "That HSP70 was reported to be a critical regulator of cardiac hypertrophy, we next set to investigate whether Asb10 overexpression-induced protection of HSP70 contributes to PE-induced hypertrophic growth in cardiomyocytes." (PMID 40399264, 2025). "Further investigations are needed to determine whether Asb10 regulates cardiac hypertrophy through its canonical role as an E3 ligase." (PMID 40399264, 2025). "We next aimed to verify whether Asb10 was downregulated in our experimental cardiac hypertrophy models." (PMID 40399264, 2025). "Since the expression of Asb10 is decreased during the progression of cardiac hypertrophy and heart failure, we asked whether overexpression of Asb10 could reverse the situation." (PMID 40399264, 2025). "Additionally, molecular markers of cardiac hypertrophy and fibrosis were found to be substantially elevated by Asb10 overexpression after TAC." (PMID 40399264, 2025). "Collectively, these results suggest that HSP70 may contribute to Asb10 overexpression induced cardiac hypertrophy by increasing cardiac inflammation and phosphorylation of HDAC2." (PMID 40399264, 2025).
cardiac hypertrophy (continued). "Furthermore, we observed that the effects of Asb10 on cardiac hypertrophy were attributed to the elevation of HSP70, cardiac inflammation, and activation of pHDAC2S394." (PMID 40399264, 2025). "We showed that Asb10 was significantly decreased in response to PE-induced cardiac hypertrophy." (PMID 40399264, 2025). "As a heart tissue-enriched E3 ligase, the function of Asb10 in cardiac hypertrophy remains unknown." (PMID 40399264, 2025). "Hence, identifying the direct binding proteins of Asb10 that regulate cardiac hypertrophy may shed light on the molecular mechanism of Asb10’s actions in the heart." (PMID 40399264, 2025). "Given that Asb10 was reported to interact with HSP70 in the development of POAG, the role of this interaction in cardiac hypertrophy and heart failure remains to be investigated." (PMID 40399264, 2025). "Our data further showed that Asb10 prevents HSP70 from undergoing STUB1-mediated ubiquitination and degradation, and HSP70-associated cardiac inflammation and HDAC2 phosphorylation may contribute to Asb10 overexpression-induced pathological cardiac hypertrophy and heart failure." (PMID 40399264, 2025). "Asb10’s ability to directly interact with HSP70 in NRVMs promoted us to ask whether this interaction leads to the degradation of HSP70, thereby playing a role in the pathogenesis of cardiac hypertrophy and heart failure." (PMID 40399264, 2025). "Collectively, these findings demonstrate that Asb10 stabilizes HSP70 via competitively inhibiting STUB1-mediated ubiquitin-dependent degradation, thereby exacerbating cardiac hypertrophy, highlighting the role of Asb10 in hemodynamic stress-induced cardiac hypertrophy and heart failure." (PMID 40399264, 2025).
cardiomyopathy (1 paper, 2025). A disease of the heart muscle or myocardium proper. "Consistent with the in vitro data, we confirmed that Asb10 was also downregulated in both mouse hypertrophic samples and human cardiomyopathy samples." (PMID 40399264, 2025).
dilated cardiomyopathy (1 paper, 2025). Cardiomyopathy which is characterized by dilation and contractile dysfunction of the left and right ventricles. "We then validated the expression of Asb10 in GEO datasets acquired from mouse cardiac hypertrophic samples, human hypertrophic cardiomyopathy samples, and human dilated cardiomyopathy samples." (PMID 40399264, 2025).
Kleefstra syndrome 2 (1 paper, 2023). "A 7q36.1q36.2 deletion containing several pathogenic genes, including DPP6, KMT2C, ASB10, PRKAG2, KCNH2, among which KMT2C is a causative gene for Kleefstra syndrome 2 (MIM#617768)." (PMID 37892645, 2023).
cardiovascular disease (1 paper, 2025). "Currently, our knowledge of Asb10 in cardiovascular disease remains limited." (PMID 40399264, 2025). "Here, we extended the role of Asb10 to cardiovascular disease." (PMID 40399264, 2025).
tumor (1 paper, 2021). "Co-staining of ASB10 with hormone receptors showed that most ASB10+ cells were located within the ERα+ tumor cell region, suggesting a positive correlation between ASB10 and ERα." (PMID 34285210, 2021). "To support this hypothesis, we first examined the expression of ASB10 in ERα-overexpressing tumor cells, which showed that ERα overexpression significantly upregulated ASB10 both at the mRNA level and the protein level." (PMID 34285210, 2021).
ASB10 also shares sentences with these, for which no sentence is quoted: Primary Open Angle Glaucoma (4 papers); triple-negative breast carcinoma (2); autism spectrum disorder (1); breast carcinoma (1); cancer (1); cardiac disease (1); channelopathies (1); deafness (1); diabetes (1); gout (1); heart failure (1); hypertrophic cardiomyopathy (1); hypertrophy (1); inflammation (1); Intellectual disability (1); myotonic dystrophy type 1 (1); nail-patella syndrome (1); normal tension glaucoma (1); osteogenesis imperfecta (1); resistant hypertension (1); Stroke (1); Treacher-Collins syndrome (1).